IL27 (interleukin 27)
Diseases named in the same sentence as IL27 in open-access papers (continued):
Sharing a sentence is not in itself a finding about the gene and the disease.
colorectal cancer (7 papers, 2014 to 2025). A primary or metastatic malignant neoplasm that affects the colon or rectum. "A single-nucleotide polymorphism (rs153109) in the IL-27 gene is associated with risk of colorectal cancer with carriage of the G allele conferring risk; however, the biological consequences of this allele on IL-27 expression and function is unclear." (PMID 35336801, 2022). "This appeared to conflict with the observation that IL-27 induced pSTAT1 in a human colorectal cancer cell line." (PMID 37153622, 2023). "The influences of IL-27 and mechanisms of action on IBD-associated colorectal carcinogenesis will need further exploration in human colorectal cancer models." (PMID 35336801, 2022). "It is not known if IL-27 or its specific receptor IL-27Rα is increased in human colorectal cancer, nor the biological consequence of this." (PMID 35336801, 2022). "There is one study showing the coexpression of CEACAM1 and TIM-3 molecules on CD8+ T cell in a mouse colorectal cancer model and human colorectal cancer patients, and CEACAM1 can be upregulated by IFN-γ and interleukin-27, leading to the suggestion that CEACAM1 may be a phenotype of failing T cells." (PMID 36712923, 2023). "We therefore tested the human colorectal cancer cell line HCT-116 and confirmed that, unlike our finding in mouse colonoids, IL-27 induced pSTAT1." (PMID 37153622, 2023).
endometriosis (7 papers, 2017 to 2025). The growth of functional endometrial tissue in anatomic sites outside the uterine body. "The role of IL27 gene polymorphisms in endometriosis remains insufficiently explored." (PMID 39767772, 2024). "One article showed that interleukins IL-2 and IL-27 work together to enhance the growth and invasion of endometriotic stromal cells by regulating the balance between IFNγ and IL-10 in the context of endometriosis." (PMID 39767772, 2024). "And IL-27 was considered to induce the IL-10 and IL-17A double-producing Th17 cells in endometriosis." (PMID 35582411, 2022). "This combined effect of multiple factors in the peritoneal cavity or ectopic lesion led to an increased level of IL-27 by macrophages in endometriosis." (PMID 28300844, 2017). "In advanced endometriosis, the formation of a c-Maf, RORγt and Blimp-1 complex triggered by IL-27 contributes to the expansion of IL-10-producing Th17 cells." (PMID 28300844, 2017). "Here, we report that IL-10+Th17 cells are significantly increased in the peritoneal fluid of women with endometriosis, along with an elevation of IL-27, IL-6 and TGF-β." (PMID 28300844, 2017). "Additionally, studies have demonstrated that the immune factor IL-27 in endometriosis accelerates the development of endometriosis by triggering the production of IL-10 by Th17 and promoting the proliferation and implantation of ectopic lesions." (PMID 38627726, 2024). "Most current research focuses on various other cytokines and their roles in endometriosis, but IL-27 has not been widely investigated as a potential diagnostic biomarker." (PMID 39767772, 2024). "There appears to be a lack of studies specifically measuring IL-27 concentrations in serum and peritoneal fluid among patients with endometriosis." (PMID 39767772, 2024). "IL-27 inhibits Th17 differentiation, and promotes the production of IL-10 in Th17 cells by the c-Maf/RORC/Blimp-1 complex, participating in the formation of an immune tolerance pattern in the late stage of endometriosis." (PMID 28300844, 2017).
multiple myeloma (7 papers, 2013 to 2021). "IL-27 strongly inhibited tumor growth and in vivo tumorigenicity of multiple myeloma cells through suppression of angiogenesis." (PMID 24155891, 2013). "In patients with multiple myeloma, serum as well as bone marrow levels of IL-27 decrease whilst IL-17 increases in line with disease progression, with a high IL-27 : IL-17 ratio (i.e., high IL-27 and low IL-17) in the bone marrow associated with better prognosis." (PMID 25110397, 2014). "It has previously been shown that IL-27 has anti-angiogenic activity by down regulating the expression of VEGF, IL-8/CXCL8 and CXCL5 in human multiple myeloma cells." (PMID 24274066, 2013).
myocardial infarction (7 papers, 2012 to 2025). Gross necrosis of the myocardium, as a result of interruption of the blood supply to the area, as in coronary thrombosis. "In our patient cohort, elevated IL-27 levels were associated with major long-term clinical outcomes, including myocardial infarction, stroke, major amputation, and coronary and peripheral revascularization." (PMID 41302192, 2025). "One study in 524 patients with acute coronary syndrome has shown that patients with IL-27 levels in the highest tertile have a 2.7-fold higher risk of recurrent myocardial infarction or cardiovascular death when compared to patients with IL-27 in the lowest tertile." (PMID 41302192, 2025). "Serum levels of IL-27, IL-4, IL-17, and interferon (IFN)-γ in healthy subjects as well as patients with ACS, including stable angina pectoris (SA), unstable angina pectoris (UA), and acute myocardial infarction (AMI), were determined using an enzyme-linked immunosorbent assay." (PMID 30631648, 2019). "Regarding blood IL-27 levels and atherosclerotic diseases, several studies reported high blood IL-27 levels in patients who had acute coronary syndrome (ACS), defined as acute myocardial infarction (MI) or unstable angina pectoris (UAP)." (PMID 38786961, 2024). "IL-27′s enhancement of TNF-α mediated upregulation of adhesion molecules and pro-inflammatory IL-6 in blood monocytes of patients with acute myocardial infarction (MI) makes it high CVD risk associated." (PMID 35327515, 2022). "Plasma IL-35, IL-10, TGF-β1, IL-12 and IL-27 levels were measured using an ELISA in 43 stable angina pectoris (SAP) patients, 62 unstable angina pectoris (UAP) patients, 56 acute myocardial infarction (AMI) patients and 47 chest pain syndrome patients as a control group." (PMID 23285065, 2012).
visceral leishmaniasis (7 papers, 2012 to 2025). A severe form of leishmaniasis characterized by irregular bouts of fever, substantial weight loss, swelling of the spleen and liver, and anemia (which may be serious). "Here we studied the role of IL-27 signalling in experimental visceral leishmaniasis (VL) caused by infection of C57BL/6 mice with the human pathogen Leishmania donovani." (PMID 33049000, 2020). "In a study of human visceral leishmaniasis, pro-inflammatory cytokines acting on splenic macrophages had the potential to upregulate IL-27, which in turn induced IL-21 to expand IL-10+CD4+CD25−Foxp3− T cells as a mechanism of positive feedback control." (PMID 29033934, 2017). "Based on observational data, it has been proposed that plasma IL-6 and IL-8, IFN-γ, IL-27, and soluble CD14 are the major mediators of the pathogenicity of kala-azar." (PMID 40732663, 2025).
autoimmune uveitis (6 papers, 2014 to 2023). An autoimmune form of uveitis (disease). "Interleukin-27 is constitutively secreted by microglia in the retina or brain, and upregulation of IL-27 during neuroinflammation suppresses encephalomyelitis and autoimmune uveitis." (PMID 35897732, 2022). "Our data support the potential role of IL-27 in treating autoimmune uveitis by countering these proinflammatory cytokines." (PMID 34299138, 2021). "In conclusion, IL-27 and STAT1 are potential biological agents to help prevent autoimmune uveitis." (PMID 33816637, 2021). "We recently reported that decreased IL-27 serum levels were also found in an autoimmune uveitis entity, Vogt-Koyanagi-Harada syndrome, but not in a group of patients with active acute anterior uveitis." (PMID 24887071, 2014).
glioma (6 papers, 2014 to 2024). A benign or malignant brain and spinal cord tumor that arises from glial cells (astrocytes, oligodendrocytes, ependymal cells). "Examples include IL27, which promotes anti-tumor immunity, and growth hormone, which increases NK cell cytotoxicity to glioma cells." (PMID 25952672, 2015).
pancreatic cancer (6 papers, 2009 to 2025). "In the pancreatic cancer preclinical model, IL27 production induced T-cell exhaustion, resulting in resistance to immunotherapy." (PMID 36713514, 2022). "IL-27 was also able to sensitize the pancreatic cancer cells to gemcitabine, a chemotherapeutic drug, in the co-culture system." (PMID 31681561, 2019). "We first evaluated the influence of IL-12 and IL-27, as single agents and in association, on the polarization of CEA-specific Th2 CD4+ T cell clones from a pancreatic cancer patient." (PMID 19798410, 2009). "Here, we report a novel vaccinia virus (VV), VVLΔTKΔN1LΔA41L (with deletion of thymidine kinase (TK), N1L, and A41L genes) armed with interleukin 27 (IL-27), that can cure established tumors and promote long-term antitumor immunity in murine pancreatic cancer tumor models." (PMID 40350204, 2025). "Moreover, the presence of IL-27 reduced proliferation, migration, and invasion of pancreatic cancer cell lines co-cultured with M2 polarized macrophages." (PMID 31681561, 2019). "Additionally, IL-27 is also reported to promote cell apoptosis in human pancreatic carcinoma Aspc1 cells." (PMID 28746469, 2017).
sarcoidosis (6 papers, 2013 to 2025). Sarcoidosis is a multisystemic disorder of unknown cause characterized by the formation of immune granulomas in involved organs. "Many T-cell-associated cytokines have been implicated in the immunopathogenesis of sarcoidosis, but it is becoming apparent that IL-12 cytokine family members including IL-12, IL-23, IL-27, and IL-35 are also involved." (PMID 25386143, 2014). "The cytokine has recently been shown to be chemotactic for human DC and to impair HLA Class I antigen presentation in those cells and as the latter is believed to cause granuloma formation, IL-27 might thus also alter antigen presentation in sarcoidosis." (PMID 25386143, 2014). "There are theories regarding a link between sarcoidosis and cytokines, including Th1, IL-2, IL-6, IL-8, IL-12, IL-18, IL-27, interferon gamma, and tumor necrosis factor." (PMID 40259952, 2025). "Many of this module’s immunologic pathways have been implicated in the pathogenesis of sarcoidosis including aberrant T cell signaling, the IL17 pathway as well as IL12, IL27, and IL23 family of cytokines." (PMID 27460362, 2016). "Compared to healthy controls, T-bet mRNA levels were lower in sarcoidosis patients (p = 0.010), while IL-27 mRNA levels were higher in sarcoidosis patients (p = 0.019)." (PMID 26254778, 2015). "The mean IL-27 concentrations were 3.1 ± 4.2 pg/ml (mean ± SD) in controls and 1.8 ± 3.0 pg/ml in sarcoidosis patients." (PMID 26254778, 2015). "We also documented elevated IL-27 mRNA and IL-27p28 levels in PBMCs of sarcoidosis patients compared to controls." (PMID 26254778, 2015). "This study is the first to demonstrate increased PBMC IL-27 mRNA expression in sarcoidosis patients compared to healthy controls." (PMID 26254778, 2015). "This is the first study to detect IL-27 in EBC of sarcoidosis patients." (PMID 26254778, 2015). "Our data indicate that depressed T-bet mRNA and protein expression could contribute to the peripheral anergy in sarcoidosis and that IL-27 mRNA levels are elevated in the PBMC from those with sarcoidosis." (PMID 26254778, 2015). "IL-27 was detected in 6/20 controls and 6/18 sarcoidosis patients." (PMID 26254778, 2015). "Although one may conclude that IL-27 may not be implicated in the immunopathogenesis of pulmonary sarcoidosis, all 6/18 sarcoidosis patients who had detectable IL-27 EBC levels had pulmonary sarcoidosis." (PMID 26254778, 2015). "The overstimulation of cytokines, such as IL-12, IL-18, IL-27, and interferon (IFN)-gamma, has been postulated in lung sarcoidosis pathogenesis." (PMID 31358038, 2019). "A cross-sectional study was conducted to investigate the expression of TH1 cytokines and transcription factors (IFNγ, IL-27 and T-bet) in the peripheral blood and/or EBC of sarcoidosis patients and healthy controls." (PMID 26254778, 2015). "There was a significant trend to elevated IL27p28 levels in the plasma from sarcoidosis patients but not in the IL-27 assay, suggesting that the levels are low and very sensitive assays are required." (PMID 26254778, 2015). "Sarcoidosis has often been termed an “immune paradox” as there is peripheral anergy to common recall antigens despite pronounced TH1-dominant inflammation at disease sites, such as the lung, with up-regulation of interferon γ, IL-27 and transcription factors." (PMID 26254778, 2015). "EBC IL-27 levels were not significantly different between sarcoidosis controls and patients." (PMID 26254778, 2015). "There are, to our knowledge, no studies on IL-27 in peripheral blood mononuclear cells (PBMCs) and EBC of sarcoidosis patients." (PMID 26254778, 2015).
type 2 diabetes (6 papers, 2024 to 2025). "Previous studies have shown that IL-27 levels are decreased in obese individuals and IL-27 level is inversely associated with fasting blood glucose level in type 2 diabetes." (PMID 39716461, 2025). "Evidence from experimental and clinical studies suggests that IL-27 plays a dual role in the pathogenesis of both type 1 and type 2 diabetes, with its effect being dependent on disease context, the immune environment, and disease stage." (PMID 40804870, 2025). "In type 1 and type 2 diabetes, IL-27 exhibits stage-dependent effects; it exacerbates pancreatic β-cell damage in early inflammation but later mitigates disease progression by suppressing Th17 responses and reducing antigen-presenting cell activity." (PMID 39906735, 2024).
allergic asthma (5 papers, 2012 to 2024). A asthma with a basis in a pathological type I hypersensitivity reaction. "Together, these results demonstrate that preventative administration of exogenous IL-27 effectively alleviates Th2-mediated allergic asthma." (PMID 27687913, 2016).
coronary atherosclerosis (5 papers, 2015 to 2025). Atherosclerosis of the coronary vasculature. "miR-379-5p was found to be upregulated and has been associated with early vascular alterations through its interaction with IL-27 polymorphisms, showing functional relevance in asymptomatic coronary atherosclerosis within the Mexican population." (PMID 40943645, 2025). "On the other hand, IL-27 is a covalent double-stranded cytokine, which can combine with various immune cells, mediate the immune system, and involve in the coronary atherosclerosis." (PMID 34956579, 2021). "In patients with coronary atherosclerosis, increased levels of both IL-27 and NLRP3 inflammasome components are reported and are also associated with disease severity." (PMID 29176764, 2017). "Our study in patients with peripheral artery disease align with these two studies focusing on coronary atherosclerosis: in our analysis, circulating IL-27 levels in the highest tertile independently predicted a 3.6-fold increase in the risk of major cardiovascular events." (PMID 41302192, 2025).
graft versus host disease (5 papers, 2017 to 2025). An immune system disorder that occurs after allogeneic hematopoietic stem cell transplant and is a reaction of donor immune cells against host tissues. "Blocking the IL-27 pathway prevented graft-versus-host disease (GVHD), which suggested that IL-27 accelerates acute rejection." (PMID 32075272, 2020). "IL-27 plays a pro-inflammatory role in graft versus host disease (GVHD) biology, as blocking of IL-27 signaling reduced GVHD in mice through augmenting Treg reconstitution." (PMID 28612255, 2017). "Other studies have enhanced wild-type L. lactis to secrete IL-27 to treat immune colitis, and genetically modified Lactobacillus reuteri to secrete IL-22 for conditions such as IBD and Graft versus Host Disease (GvHD)." (PMID 39233526, 2024).
interstitial lung disease (5 papers, 2016 to 2024). A diverse group of lung diseases that affect the lung parenchyma. "With regard to the human counterpart, serum IL-27 levels are increased in RA and seem to be directly correlated with disease activity and RA-associated interstitial lung disease (ILD)." (PMID 30886947, 2017). "However, Xia reported that serum IL-27 was markedly elevated in patients with SS and was particularly associated with interstitial lung disease." (PMID 31754394, 2019). "SS patients tend to have higher IL-27 levels than healthy subjects, and such levels in SS patients with interstitial lung disease are higher than those of SS patients without it." (PMID 34630072, 2021). "Moreover, higher levels of IL-27 were measured in patients with interstitial lung disease (ILD)." (PMID 26932661, 2016). "Serum levels of IL-27 in patients with SS with or without interstitial lung disease (ILD) were both higher than that in healthy controls, and serum levels of IL-27 were higher in patients with SS with ILD than that in patients with SS without ILD." (PMID 38566992, 2024). "Serum levels of IL-27 were higher in patients with RA with interstitial lung disease (ILD) than that in patients without ILD." (PMID 38566992, 2024).
lymphoma (5 papers, 2013 to 2022). A malignant (clonal) proliferation of B- lymphocytes or T- lymphocytes which involves the lymph nodes, bone marrow and/or extranodal sites. "We previously reported that lymphoma cell-derived IL-27 significantly enhanced PD-L1 expression on TAMs via the STAT3 pathway." (PMID 35835809, 2022). "Lymphoma cell line supernatant or IL-27 induced PD-L1/2 expression in human macrophages through a STAT3-dependent mechanism." (PMID 28255204, 2017). "In previous analyses, we observed that one subunit of IL-27, EBI3, was expressed at high levels by tumor cells in specific forms of lymphomas such as Hodgkin lymphoma, EBV or HTLV1-associated lymphoproliferative diseases and diffuse large B-cell lymphomas." (PMID 24130734, 2013). "IL-27 increases PDL1 expression in human lymphoma macrophages." (PMID 34234781, 2021). "It has been proposed that EBI3 produced by lymphoma cells may pair with macrophage-released IL-27p28 to form the IL-27 heterodimer, which induces PD-L1/2 expression." (PMID 28255204, 2017). "A lymphoma study reported that IL-27-induced upregulation of PD-L1 in macrophages could be mitigated by STAT3 inhibition, indicating that IL-27 may regulate PD-L1 expression in macrophages via STAT3." (PMID 31781673, 2019).